JAK3 (Janus kinase 3)
Diseases named in the same sentence as JAK3 in open-access papers (continued):
Sharing a sentence is not in itself a finding about the gene and the disease.
lymphoma (24 papers, 2010 to 2025). A malignant (clonal) proliferation of B- lymphocytes or T- lymphocytes which involves the lymph nodes, bone marrow and/or extranodal sites. "Using the lymphoma knowledge graph as an example, we uncovered a pathogenic mutation in JAK3, which is associated with the IL-2 signaling pathway and affects adenosine triphosphate metabolism." (PMID 41334179, 2025). "In this study, we demonstrated that the JAK3/STAT5 pathway is activated in T/NK cell lines from EBV-associated lymphoma, and that the inhibition of such activation by tofacitinib results in a decrease in cell growth." (PMID 27732937, 2016). "Moreover, mutations of SOCS-1 that abolished its binding to JAK3 reinforced the aggressive course of the lymphoma." (PMID 34948183, 2021). "First, we transduced the IL-2 indicator cell line MO7e with lentiviral expression vectors encoding the wild-type form of JAK3, the constitutive-active, and lymphoma-associated variant JAK3-A572V, or the JAK3-R840C variant, and analyzed IL-2-dependent growth at increasing IL-2 concentrations." (PMID 29375547, 2017). "Using this model we reveal a two-step mutational process reflecting disease progression, whereby an activating JAK3 mutation known to drive lymphoma formation is joined in progressed disease by novel inactivating mutations of SOCS1, thereby weakening the latter's inhibitory potency." (PMID 27144517, 2016). "On a genetic level, these lymphomas show frequent gains of 8q24 (including MYC gene) and recurrent mutations of STAT5b, JAK3, GNAI2, and SETD2." (PMID 37345080, 2023). "In a series of 84 ENKTL lymphomas sequenced for JAK3 and STAT3, JAK3 mutations were discovered in 7% of cases, while STAT3 mutations were less common, with only one case found to be mutated." (PMID 35628826, 2022). "IL-15 is a proinflammatory cytokine that contributes STAT activation by mediating JAK1 and JAK3 phosphorylation, leading to lymphoma cell growth and survival." (PMID 34079795, 2021). "In the ENKTCL arising in East Asia, genetic analyses have shown that activating mutations of the JAK-STAT pathway, such as in JAK3 (5–35%), STAT3 (6–27%) and STAT5B (2–6%) genes are characteristic of this lymphoma." (PMID 32759793, 2020). "The detection of pY841 within A573V JAK3 and in various T-cell leukemia/lymphoma cell lines suggests that this site might serve as a unique biomarker for hyperactive kinase activity." (PMID 37569303, 2023). "To further evaluate the specificity of NSC114792 for JAK3 inhibition, we used the rat pre-T lymphoma cell line Nb2 and the murine myeloid progenitor cell line 32D stably expressing IL-2Rβ (32D/IL-2Rβ), both of which have been previously used to study cytokine-dependent activation of JAK proteins." (PMID 20149240, 2010). "Furthermore, this compound was found to lower the levels of phosphorylated STAT3 and Janus kinase-3 (JAK3), which may be a significant factor in the reduction of cell viability, cell cycle arrest, and activation of apoptosis in lymphomas." (PMID 38397437, 2024). "Both compounds inhibited the IL-4 pathway by acting on IL-4Rα, JAK3, and STAT6 activation in lymphoma cells (DND39) and fibroblasts (NIH3T3)." (PMID 36364420, 2022). "In advanced stages of a lymphoma, STAT3 and STAT5 are completely dependent on the constitutively activated JAK1 and JAK3." (PMID 34948183, 2021).
breast carcinoma (23 papers, 2010 to 2025). "The co-occurrence of JAK1 and JAK3 mutations with other genetic alterations has also been observed in solid cancers, such as breast cancer." (PMID 37140667, 2023). "In support of this, a recent study identified somatic JAK3 mutations in patients with breast carcinomas and gastric carcinoma." (PMID 20149240, 2010). "Similarly, activating JAK3 mutations such as V722I have been identified in acute megakaryoblastic leukemia and NK/T-cell lymphoma, and only in a few cases of gastric and breast cancer." (PMID 25656989, 2015). "For 31 hormone receptor (HR)+/HER2− breast cancers, there were two clusters: One with the co-occurrence of ATM, FGFR1, and WT1 frameshift mutations, and the other with JAK3 splice site and FGFR2 frameshift mutations." (PMID 34203389, 2021). "In contrast, PLD2 phosphorylates Janus Kinase3 (JAK3) has been reported to promote cell invasion in breast cancer." (PMID 35127525, 2021). "Recent breast cancer models in mice have also indicated increased FES expression as linked to tumor aggressiveness, macrophage infiltration, and involvement in the JAK3‐Fes‐PLD2 signaling pathway." (PMID 34189853, 2021). "Aberrantly elevated expression of IL-7 and its signaling complex including Jak-3 and PI3-K is associated with aggressive human breast cancer and IL-7 significantly accelerates the growth of breast cancer cells in vitro." (PMID 34575268, 2021). "Moreover, activation of the PLD2-Fes-Jak3 signaling pathway can accelerate the proliferation and invasion of breast cancer cells." (PMID 32256211, 2020). "For instance, JAK3 was demonstrated to promote breast cancer metastasis." (PMID 32051510, 2020). "Therefore, we speculate that the JAK3 pathway may also related to breast cancer and play a key role in Stigmasterol-inhibited BCSC activity." (PMID 39991585, 2025). "The heatmaps of the 10 HR−/HER2+ breast cancers were homogeneous, while for 9 HR-/HER2− cases, a major cluster with ATM, FGFR1, and WT1 frameshift mutations (n = 6 for ATM1, FGFR1 and n = 5 for WT1) and a minor one with JAK3 splice site mutations were prominent (n = 3)." (PMID 34203389, 2021). "This study uniquely explores Melittin’s interactions with JAK2, JAK3, and STAT3, which are crucial components of breast cancer signaling pathways." (PMID 40243485, 2025). "These compounds are predicted to stably interact with the MMP12, CDK4, JAK3, VEGFR2, MMP13, VEGFR1, and KCNA3 proteins, which have a role in inhibiting the growth and inducing apoptosis in breast cancer cells." (PMID 36106139, 2022). "ODZ10117 did not significantly inhibit the JAK family of tyrosine kinases, including JAK1, JAK2, JAK3, and TYK2, in breast cancer cells and Hodgkin’s lymphoma cells." (PMID 31684051, 2019). "CaMKII, JAK-3, and IKK inhibitors decreased the proportion of ALDH-positive breast cancer cells and CD44high/CD24low subpopulation." (PMID 28289331, 2017). "Further studies are necessary to elucidate the molecular mechanism of anti-CSC effects of CaMKII, JAK-3 and IKK inhibitors in breast cancer with a validation in animal model of breast cancer." (PMID 28289331, 2017). "To further confirm the role of CaMKII, JAK-3, and IKK kinase in CSC formation, we investigated the effect of these kinase inhibitors on proportion of breast cancer cells with ALDH activity and CD44high/CD24low-expressing subpopulation in MCF-7 cells." (PMID 28289331, 2017). "In contrast, Hodgkin's lymphoma HLDM-2 cells, breast cancer MDA-MB-468 cells and prostate cancer DU145 cells exhibited high levels of phospho-JAK1 and -JAK2 but not phospho-JAK3." (PMID 20149240, 2010).
psoriasis (20 papers, 2012 to 2026). An autoimmune condition characterized by red, well-delineated plaques with silvery scales that are usually on the extensor surfaces and scalp. "In CD18-deficient mice with a psoriasis-like phenotype, the active metabolite of R348, R333 (Rigel Pharmaceuticals, San Francisco CA, USA), inhibits Jak3- and Syk-dependent pathways and reduces cellular Th1 and Th2 immune responses." (PMID 24170986, 2013). "Moreover, recent report suggests an association between Jak1 rs310241 and Jak3 rs3008 polymorphisms in the risk of developing psoriasis, an epithelial abnormality." (PMID 33814980, 2021). "In psoriasis and PsA, tofacitinib (a JAK3/1 inhibitor) is an approved therapy that improves both skin and joints." (PMID 40861474, 2025). "Our results indicate that psoriasis is mainly a JAK3 and JAK1 driven disease with a predominance of STAT3 signaling." (PMID 27711196, 2016). "Tofacitinib, one of the most investigated JAK inhibitors in the treatment of psoriasis, shows impressive beneficial responses with JAK3 as their predominant target." (PMID 27711196, 2016). "Tofacitinib, a pan-JAK inhibitor with predominant anti-JAK3 effect, has shown promising results in the treatment of psoriasis both orally and topically." (PMID 27711196, 2016). "Phase I and II clinical trials on tofacitinib, a JAK1 and JAK3 inhibitor, reported dose-dependent improvement in patients with psoriasis when compared to the placebo groups." (PMID 24883332, 2014). "In conclusion, previous studies have reported that oral astilbin could inhibit Th17 cell differentiation and ameliorate IMQ‐induced psoriasis‐like skin lesions by inhibiting the Jak3/Stat3 signalling pathway in BALB/c mice." (PMID 35023281, 2022). "In vitro, JAK3/STAT3 signaling acts as a target in the treatment of psoriasis models." (PMID 27711196, 2016). "In contrast, AA, psoriasis and LP carry mainly a JAK3 signature which suggests that specific JAK3 inhibition could be sufficient." (PMID 27711196, 2016). "In psoriasis, keratinocytes, which also express JAK3 are among such target cells." (PMID 24170986, 2013). "Because the JAK3-mediated step of the signaling cascade is critical for immune cell development and differentiation, its targeting may be beneficial for the treatment of many autoimmune conditions, such as psoriasis." (PMID 24170986, 2013). "In conclusion, PLO treatment ameliorated IMQ-induced psoriasis by enhancing antioxidant defenses, and by inhibiting JAK2 and JAK3/STAT3 signaling, supporting its potential as a therapeutic candidate for psoriasis." (PMID 42306466, 2026). "In contrast, psoriasis and LP showed only JAK1 and JAK3 upregulation, while AA and CLE were characterized by a single dermal JAK signal (pJAK3 and pJAK1, respectively)." (PMID 27711196, 2016). "Secondly, a single patient with alopecia universalis and psoriasis was treated orally with tofacitinib, an FDA approved JAK inhibitor with higher affinity to JAK3, and also showed a clinical response." (PMID 26137574, 2015). "Tofacitinib, a JAK1 and JAK3 inhibitor, and ruxolitinib, a JAK1 and JAK2 inhibitor, are the most extensively studied JAK inhibitors in psoriasis." (PMID 24883332, 2014). "Tofacitinib, a JAK1 and JAK3 inhibitor, has undergone the most extensive clinical studies of JAK inhibitors in psoriasis treatment." (PMID 24883332, 2014). "Tofacitinib, an oral or topically administered JAK1 and JAK3 inhibitor, and ruxolitinib, a topical JAK1 and JAK2 inhibitor, have been most extensively studied in psoriasis, and both improved clinical symptoms of psoriasis." (PMID 24883332, 2014). "Inhibition of Janus kinase 3 (JAK3) in T-cells is expected to block T-cell receptor-triggered signaling from downstream events and could be effective in T-cell-mediated disorders such as psoriasis." (PMID 35203438, 2022).
alopecia areata (18 papers, 2016 to 2026). Loss of scalp and body hair involving microscopically inflammatory patchy areas. "Ritlecitinib (LitfuloTM) is a kinase inhibitor, acting on Janus kinase 3 and tyrosine kinase, used for the treatment of severe hair loss (alopecia areata)." (PMID 38338330, 2024). "Ritlecitinib is an oral JAK3/TEC family kinase inhibitor approved for individuals aged ≥ 12 years with severe alopecia areata." (PMID 41645877, 2026). "Ritlecitinib, a second-generation JAK3 inhibitor, is a novel therapeutic agent for alopecia areata and other autoimmune conditions." (PMID 39861185, 2025). "Ritlecitinib is an oral Janus kinase 3/tyrosine kinase expressed in hepatocellular carcinoma (JAK3/TEC) family kinase inhibitor approved for the treatment of severe alopecia areata (AA)." (PMID 39812238, 2025). "JAK3 was found to be overexpressed also in human alopecia areata; the investigation of its role in animals should be proven." (PMID 37624299, 2023). "JAK3 was strongly expressed also in alopecia areata; JAK1 and JAK2 were to a lesser extent also elevated." (PMID 37624299, 2023). "In this regard, it is important to notice that JAK3 was found to be the only JAK overexpressed in human alopecia areata compared to controls." (PMID 37624299, 2023). "Patients with alopecia areata have elevated JAK3 protein levels in the epidermis and phosphorylated JAK3 in the dermal infiltrate." (PMID 29928283, 2018). "Alopecia areata lesions also exhibit upregulated expression of genes, such as CCL19, IL-2, IL-15/IL-15RA, IL-2RA/IL-2RB, and Janus kinase 3 (JAK3) responsible for T cell migration and activation compared to regions with normal hair growth in alopecia areata patients." (PMID 29928283, 2018). "This subgroup analysis of the ALLEGRO phase 2b/3 study (NCT3732807) assessed the efficacy and safety of multiple doses of ritlecitinib, an oral JAK3/TEC family kinase inhibitor, in Asian patients with alopecia areata (AA)." (PMID 40071721, 2025). "Ritlecitinib, an oral JAK3/TEC family kinase inhibitor, demonstrated efficacy over 48 weeks in patients with alopecia areata (AA) in the ALLEGRO phase 2b/3 study." (PMID 39962358, 2025). "Ritlecitinib is a selective inhibitor, acting on Janus kinase 3 (JAK3) and tyrosine kinase family (TEC) and it is indicated for the treatment of alopecia areata in adults and young people aged 12 years and older." (PMID 39859036, 2025). "Ritlecitinib (1-[(2S,5R)-2-methyl-5-(7H-pyrrolo[2,3-d]pyrimidin-4-ylamino)piperidin-1-yl]prop-2-en-1-one; WHO ACT code L04A-F08; CAS No: 1792180-81-4; PF-06651600) is an irreversible inhibitor of JAK3 and TYK2 that Pfizer is developing under the trade name LITFULOTM for treatment of alopecia areata." (PMID 39861185, 2025).
ulcerative colitis (18 papers, 2012 to 2025). An inflammatory bowel disease involving the mucosal surface of the large intestine and rectum. "The tissue-specific role of Jak3 also shows association between ulcerative colitis and hepatic inflammation in both IEC-Jak3-KO and Imm-Jak3-KO groups indicating essential roles of both IEC-specific and immune cell-specific Jak3 in maintaining tissue homeostasis and immunotolerance." (PMID 33814980, 2021). "Tofacitinib, an inhibitor of JAK1 and JAK3, has superior effects on the induction and maintenance treatment of ulcerative colitis." (PMID 39439890, 2024). "Some physicians suggest tofacitinib, a small molecule compound target JAK1 and JAK3, could be applied in the treatment of COVID-19, and tofacitinib success in treating a COVID-19 patient complicated with ulcerative colitis." (PMID 32754163, 2020). "Tofacitinib, a JAK inhibitor targeting predominantly JAK1 and JAK3, has been approved for the treatment of ulcerative colitis (UC), and there are other specific JAK inhibitors under development that may be effective in Crohn’s." (PMID 30930775, 2019). "Tofacitib, which targets JAK3 as well as both JAK1 and JAK2, and is approved for use in rheumatoid and psoriatic arthritis and ulcerative colitis, has been shown to be highly effective in cell line models of various JAK3 GOF mutations." (PMID 38474223, 2024). "The broad JAK inhibitor tofacitinib (JAK1 and JAK3 inhibitor) showed promising results for patients with ulcerative colitis but not for Crohn's disease." (PMID 34141714, 2021).
acute lymphoblastic leukemia (13 papers, 2010 to 2025). Leukemia with an acute onset, characterized by the presence of lymphoblasts in the bone marrow and the peripheral blood. "The expression of JAK3 is also upregulated with a strong activity in the B-lineage acute lymphoblastic leukemia patients; besides, JAK3 protein site mutation is reported to be the regulatory gene in the development of different disorders." (PMID 38095643, 2023). "Downregulation/mutation in the BLNK gene has been shown to induce acute lymphoblastic leukemia through JAK3 signaling." (PMID 35629968, 2022). "JAK3 has been shown expressed primarily in hematopoietic cells and is frequently mutated in T-lineage acute lymphoblastic leukemia." (PMID 32234966, 2020). "Recent studies identified somatic mutations of JAK3 in a minority of acute megakaryoblastic leukemia patients, in a high-risk childhood acute lymphoblastic leukemia (ALL) case, and in cutaneous T-cell lymphoma patients." (PMID 20149240, 2010). "Recent studies identified somatic mutations of JAK3 in a minority of acute megakaryoblastic leukemia patients, in a high-risk childhood acute lymphoblastic leukemia case, and in cutaneous T-cell lymphoma patients." (PMID 20149240, 2010). "Sustained activation of the JAK-STAT signaling pathway is a key driver in the initiation and progression of T-cell acute lymphoblastic leukemia (T-ALL), with activating mutations in JAK1 (e.g., V658F) and JAK3 (e.g., M511I) commonly reported in T-ALL cases." (PMID 41438753, 2025). "Another study reports that mitochondrial apoptosis resistance is strongly associated with activating mutations of JAK3 in T-cell acute lymphoblastic leukemia (T-ALL)." (PMID 38891056, 2024). "For example, a suite of mutations that increase the flux through the IL-7R/JAK1/JAK3/STAT5 pathway have been reported in acute lymphoblastic leukemia (ALL)." (PMID 38254802, 2024). "PHF6 mutations, often found alongside JAK3 mutations in T-cell acute lymphoblastic leukemia (T-ALL) patients, play a critical role in cancer progression by modulating signaling pathways." (PMID 38813086, 2024). "Mutations in Janus kinase 3 (JAK3) occur frequently in T-cell acute lymphoblastic leukemia (T-ALL) and are able to drive cellular transformation and the development of T-ALL in mouse models." (PMID 30764532, 2019). "Recent studies of acute lymphoblastic leukemia have identified activating mutations in components of the interleukin-7 receptor complex (IL7R, JAK1, and JAK3)." (PMID 26208852, 2015). "Somatic JAK3 GOF mutations have also been identified in cancers affecting other hematopoietic cell lineages, such as acute megakaryoblastic leukemia (AMKL), juvenile myelomonocytic leukemia (JMML) and B cell precursor acute lymphoblastic leukemia (BCP-ALL)." (PMID 38474223, 2024).